FRG2 (FSHD region gene 2)
Synonyms: FRG2A
Tractability: No criterion of Open Targets' tractability assessment is met for any kind of drug.
Gene: Protein-coding gene on chromosome 4 (190,024,367 to 190,027,257, reverse strand). Ensembl gene ENSG00000205097.
Subcellular location: Nucleus
Gene Ontology:
Cellular component: nucleus
Genetic constraint (gnomAD): Loss-of-function variants: 9 observed, 17.64 expected, observed/expected ratio (o/e) 0.51, 90% interval 0.31 to 0.89. The synonymous counts are far from expectation, so gnomAD's model fits this gene poorly and the ratio says little. Missense variants: 114 observed, 206.51 expected, observed/expected ratio (o/e) 0.55, 90% interval 0.47 to 0.64. Synonymous variants: 49 observed, 80.71 expected, observed/expected ratio (o/e) 0.61, 90% interval 0.48 to 0.77.
Homologues: Orthologues: mouse Frg2f1 (28% identical). Paralogues in human: FRG2B (98% identical), FRG2C (94% identical).
Diseases named in the same sentence as FRG2 in open-access papers:
FRG2 is named in the same sentence as 7 diseases in open-access papers, as found by Europe PMC text mining. Sharing a sentence is not in itself a finding about the gene and the disease. The quoted sentences say what the papers report.
facioscapulohumeral muscular dystrophy (3 papers, 2007 to 2014). An autosomal dominant disorder affecting the skeletal muscles of the face, scapula, and upper arm. "The distal portion of the human 4q35 genomic region (4q35.2) contains a complex arrangement of repetitive sequences and several genes including facioscapulohumeral muscular dystrophy (FSHD) region genes 1 and 2 (FRG1 and FRG2)." (PMID 17359533, 2007).
breast carcinoma (1 paper, 2023). "We found that FRG2 potently regulates breast cancer stemness, sensitizes breast tumors to chemotherapy treatments and prevents tumor formation and progression in TNBC." (PMID 37932309, 2023). "Finally, we show that FRG2 can be used as a therapeutic target to overcome paclitaxel resistance and sensitize breast cancer cells to chemotherapy." (PMID 37932309, 2023). "Our results further suggest that FRG2 could act as a differentiation factor in breast cancer and prevent cancer stemness." (PMID 37932309, 2023). "Our results uncovered new functions for FRG2 in the context of breast cancer and chemotherapy." (PMID 37932309, 2023).
muscular dystrophy (1 paper, 2023). Muscular dystrophy (MD) refers to a group of more than 30 genetic diseases characterized by progressive weakness and degeneration of the skeletal muscles that control movement. "FRG2, facioscapulohumeral muscular dystrophy (FSHD) Region Gene 2, is a gene that was found transcriptionally activated in FSHD patients." (PMID 37932309, 2023).
rhabdomyosarcoma (1 paper, 2014). A rare aggressive malignant mesenchymal neoplasm arising from skeletal muscle. "Co-transfection of these constructs with pCS2-DUX4 or the empty pCS2 backbone in TE-671 rhabdomyosarcoma cells confirmed that the activation of FRG2 is mediated by DUX4 protein expression." (PMID 25789155, 2014).
cancer (1 paper, 2023). A tumor composed of atypical neoplastic, often pleomorphic cells that invade other tissues. "The proposed role of FRG2 as a potent suppressor of stemness is evidenced by the strong increase in cancer stem cell numbers and TBNC stemness marker expression when the FRG2 gene is silenced." (PMID 37932309, 2023). "We found that several of these genes (ATP8B3, FOXR2, FRG2, HIST1H4A) act as cancer stemness negative regulators." (PMID 37932309, 2023). "Collectively, and combined with our findings, showing increased paclitaxel resistance in these gene KOs, our results define ATP8B3, FOXR2, FRG2 and HIST1H4A as cancer stemness negative regulators, consistent with a role for these genes as potential drug (paclitaxel) sensitizers." (PMID 37932309, 2023). "Having shown that ATP8B3, FOXR2, FRG2 and HIST1H4A KOs increased paclitaxel resistance and cancer stemness in vitro, we next investigated whether these KOs could also regulate paclitaxel effects in vivo." (PMID 37932309, 2023). "Interestingly, we found several of these genes (ATP8B3, FOXR2, FRG2, HIST1H4A) to act as cancer stemness regulators, able to regulate cancer stem cell self-renewal activity and expression of the endothelial protein C receptor (EPCR), a specific stemness marker for TNBC." (PMID 37932309, 2023).
tumor (1 paper, 2023). "We also showed that FRG2 gene deletion reduced paclitaxel efficacy and promoted tumor metastasis in an in vivo orthotopic transplantation TNBC model." (PMID 37932309, 2023). "Activation of the FRG2 endogenous promoter potently inhibited tumor metastasis and strongly reduced the numbers of lung metastatic nodules in SUM159 TNBC." (PMID 37932309, 2023). "Consistent with a role as a stemness suppressor, we further found that FRG2 also acts as a potent suppressor of tumor metastasis by efficiently preventing secondary lung metastatic nodule formation in preclinical models of TNBCs." (PMID 37932309, 2023). "Moreover, ATP8B3, FOXR2, FRG2 also decreased tumor response to paclitaxel in vivo, in preclinical models of TNBC tumorigenesis." (PMID 37932309, 2023). "We found that ATP8B3, FOXR2, FRG2 and HIST1H1A gene silencing significantly enhanced TNBC cells tumor-initiating capacity as well as expression of the TNBC stemness marker, EPCR, thereby defining a new role for these genes in stemness regulation." (PMID 37932309, 2023). "Activating the endogenous FRG2 promoter to induce FRG2 gene expression significantly restored chemotherapy responses in resistant TNBC cells and led to a strong decrease in tumor volume following treatment with paclitaxel." (PMID 37932309, 2023).
FRG2 also shares sentences with these, for which no sentence is quoted: breast tumors (1 paper).